DTX2 (deltex E3 ubiquitin ligase 2)
Diseases named in the same sentence as DTX2 in open-access papers:
DTX2 is named in the same sentence as 24 diseases in open-access papers, as found by Europe PMC text mining. Sharing a sentence is not in itself a finding about the gene and the disease. The quoted sentences say what the papers report.
hepatocellular carcinoma (3 papers, 2021 to 2025). A malignant tumor that arises from hepatocytes. "Based on analysis of liver hepatocellular carcinoma (LIHC) RNA sequencing (RNA‐seq) data in TCGA, we screened for genes encoding E3 ligases and revealed that DTX2 in tumor cells might be related to immune cell infiltration in HCC tissues." (PMID 39733452, 2025). "Our discovery of the functional link between miRNA-542-3p, RFX6, and DTX2 plays critical roles in hepatocellular carcinoma and provides potential therapeutic targets for hepatocellular carcinoma treatment." (PMID 34988028, 2021).
colon cancer (2 papers, 2019 to 2023). "Specifically, an early study in colon cancer positively associated DTX2 expression with post-surgical relapse and poor outcome." (PMID 37443713, 2023). "By the same token, another study in colon cancer cells (SW620, LoVo) showed DTX2 to promote migration/invasion, increase NOTCH2 levels and trigger AKT activation." (PMID 37443713, 2023). "NOTCH1 and DTX2 were important factors in NOTCH signaling pathway and therapeutic targets in colon cancer treatment." (PMID 31596728, 2019).
glioblastoma (2 papers, 2023 to 2024). The most malignant astrocytic tumor (WHO grade IV). "Poor survival correlation with DTX2 was observed also in Glioblastoma multiforme along with the demonstration that DTX2 silencing in glioma cell lines (DBTRG, U251) inhibited both their growth and migration abilities." (PMID 37443713, 2023). "Moreover, among the different pathological types of glioma, the expression of DTX2 was highest in glioblastoma, the most malignant type, slightly lower in astrocytoma, and lower in oligoastrocytoma and oligodendroglioma." (PMID 38163902, 2024). "According to this complementary analysis, DTX2 exhibited significantly differential expression compared with normal tissue in 26 of the 33 tumors including LGG and glioblastomas." (PMID 38163902, 2024).
glioma (2 papers, 2023 to 2024). A benign or malignant brain and spinal cord tumor that arises from glial cells (astrocytes, oligodendrocytes, ependymal cells). "In this study, we showed that the high expression of DTX2 in glioma tissues was associated with poor patient prognosis." (PMID 38163902, 2024). "Through a comprehensive analysis, we determined that DTX2 was closely associated with most of the unfavorable clinical features of gliomas." (PMID 38163902, 2024). "The associations between DTX2 expression and clinical characteristics of glioma were determined by bioinformatic analysis of data from The Cancer Genome Atlas and Human Protein Atlas." (PMID 38163902, 2024). "Logistic regression analysis also demonstrated a very strong association between DTX2 expression and glioma-related clinical features." (PMID 38163902, 2024). "To elucidate the mechanisms underlying the role of DTX2 in the progression of glioma, we identified five potential downstream proteins of DTX2 described in the literature." (PMID 38163902, 2024). "In this study, we demonstrate that DTX2 is overexpressed in patients with glioma and is associated with poor prognosis." (PMID 38163902, 2024). "In this study, we explore the mechanism underlying the function of DTX2 in glioma progression." (PMID 38163902, 2024). "We also show that higher DTX2 levels are associated with lower HLTF expression in glioma." (PMID 38163902, 2024). "Our result showed that DTX2 in glioma with moderate diagnostic accuracy." (PMID 38163902, 2024). "Furthermore, a Kaplan–Meier survival plot based on the HPA data clearly revealed that high DTX2 protein level was associated with poor OS of glioma patients." (PMID 38163902, 2024). "Contrary to the knockdown results, DTX2-overexpressing glioma cells showed higher cell viability than the corresponding control cells." (PMID 38163902, 2024). "Collectively, the results of this study demonstrated the involvement of the DTX2/HLTF axis in glioma cell progression and tumor growth." (PMID 38163902, 2024). "Silencing of DTX2 suppressed glioma cell viability, colony formation, and migration and induced cell apoptosis." (PMID 38163902, 2024). "DTX2 expression was significantly higher in glioma tissues of G3/G4 grade compared with those of G1/G2 grade." (PMID 38163902, 2024). "In the transwell assay, the migration and invasion of glioma cells in the shDTX2 group were greatly reduced compared with the control group, whereas in the overexpressed DTX2 group they were greatly increased." (PMID 38163902, 2024). "Upregulation of DTX2 drove cell proliferation, migration, and invasion, whereas engineered downregulation of DTX2 had the opposite effects, consistent with the oncogenic role of DTX2 in the development of glioma." (PMID 38163902, 2024). "We observed that overexpression of DTX2 in U251 glioma cells greatly induced their tumorigenic capacity." (PMID 38163902, 2024). "BRD4 transcriptionally activates DTX2, contributing to glioma progression, and predicts an unfavorable prognosis." (PMID 38163902, 2024). "The WHO grade of glioma has a strong correlation with patient survival, and our results revealed a significant increase in DTX2 expression in tumors with increasing WHO grade." (PMID 38163902, 2024). "The expression of DTX2 in glioma tissues was detected using immunohistochemistry and western blotting." (PMID 38163902, 2024). "The results showed upregulation of HLTF expression in glioma cells with DTX2 knockdown and downregulation in the DTX2-overexpressing U87 and U251 cells, indicating a negative regulation between DTX2 and HLTF." (PMID 38163902, 2024). "All those results suggest that DTX2 suppresses glioma cell proliferation, migration, and invasion through HLTF." (PMID 38163902, 2024). "Western blotting revealed that protein levels of HLTF in glioma cells were greatly reduced after overexpression of DTX2 but was highly increased after DTX2 knockdown, indicating the negative regulation of DTX2 and HLTF." (PMID 38163902, 2024).
glioma (continued). "There was significant upregulation of DTX2 expression in glioma patients over the age of 60 years compared with younger patients." (PMID 38163902, 2024). "The cell viability of DTX2-silenced glioma cells was much lower at 72 h in both cell lines compared with controls, indicating that DTX2 repression may inhibit the development of gliomas." (PMID 38163902, 2024). "Finally, tumor xenograft experiments further verified the involvement of the DTX2/HLTF axis in tumor growth in glioma." (PMID 38163902, 2024). "DTX2 was highly expressed in glioma samples, and this was correlated with worse overall survival." (PMID 38163902, 2024). "These in vitro findings suggest that DTX2 contributes to migration and invasion of glioma cells." (PMID 38163902, 2024). "High DTX2 expression could promote glioma cell development and indicate poor prognosis of glioma patients." (PMID 38163902, 2024). "To investigate whether the effects of DTX2 on glioma depended on HLTF, we performed double knockdown of DTX2 and HLTF (shDTX2#1 + shHLTF#1) in U87 and U251 cells." (PMID 38163902, 2024). "DTX2 knockdown inhibits cell proliferation and induces apoptosis in glioma." (PMID 38163902, 2024). "Having shown that DTX2 promoted the development of glioma and negatively regulated the expression of HLTF in vitro, we next investigated whether such regulation had an effect on in vivo tumor growth in nude mice models." (PMID 38163902, 2024). "We also performed IHC staining to investigate the expression of DTX2 in clinical glioma tissues." (PMID 38163902, 2024). "We have identified DTX2/HLTF as a new axis in the development of glioma that could serve as a prognostic or therapeutic marker." (PMID 38163902, 2024). "Furthermore, we detected DTX2 and HLTF expression levels in glioma tissues by IHC and found that HLTF expression was negatively associated with DTX2 expression in 180 glioma tissues." (PMID 38163902, 2024). "All of those results indicate that DTX2 binds to HLTF in glioma." (PMID 38163902, 2024). "As E3 ubiquitin-protein ligase is likely to be involved in the regulation of protein expression, we evaluated whether DTX2 regulated the stability of HLTF protein in glioma cells." (PMID 38163902, 2024). "Therefore, we preformed immunoprecipitation on whole-cell lysates of human glioma cells transiently expressing Flag-tagged DTX2 or an empty vector to demonstrate complex formation." (PMID 38163902, 2024). "Furthermore, we found that HLTF could bind to DTX2 in glioma cells, and that the two proteins were co-located in the nucleus." (PMID 38163902, 2024). "However, the role of DTX2 in glioma progression has remained obscure." (PMID 38163902, 2024). "However, studies of DTX2 in cancer have been limited, with very few reports on its role in glioma." (PMID 38163902, 2024). "In addition, knockdown of DTX2 inhibited cell proliferation in both glioma cell lines." (PMID 38163902, 2024). "The newly identified DTX2/HLTF axis strengthens the potential oncogenic role of DTX2 and tumor suppressor role of HLTF in glioma and provides potential therapeutic markers for glioma." (PMID 38163902, 2024). "In vitro ubiquitination assays showed increased HLTF ubiquitination in DTX2 overexpressed glioma cells and decreased HLTF ubiquitination in DTX2 knockdown cells, which confirmed our assumptions." (PMID 38163902, 2024). "Here, we investigated the subcellular location of DTX2 and HLTF in glioma cells was by immunofluorescence assay." (PMID 38163902, 2024). "All these findings suggest that the DTX2/HLTF axis is crucial for glioma progression and may represent a promising target for the treatment of glioma." (PMID 38163902, 2024). "Moreover, western blotting demonstrated upregulation of DTX2 protein levels in glioma tissues compared with adjacent normal controls." (PMID 38163902, 2024).
head and neck cancer (1 paper, 2026). A primary or metastatic malignant neoplasm affecting the head and neck. "Furthermore, we demonstrate that DTX2 potentiates STING-mediated type I interferon response in multiple tumor cell lines, and enhances anti-tumor immunity in murine head and neck cancer models." (PMID 41904156, 2026).
Hypertension (1 paper, 2017). The presence of chronic increased pressure in the systemic arterial system. "SNVs in Dtx2, Upk3b and Upk3bl were found to be significantly associated with both insulin resistance and hypertension." (PMID 28130354, 2017). "Three genes within the chromosome 12 congenic strain interval (Dtx2, Upk3b, Upk3bl) contain SNVs that were significantly associated across 42 rat strains with both hypertension and insulin resistance." (PMID 28130354, 2017).
lung carcinoma (1 paper, 2025). "DTX2, an E3 ubiquitin ligase, exhibits significantly elevated expression in non-small-cell lung cancer (NSCLC) and regulates lung cancer cell proliferation through the ferritinophagy and ferroptosis pathways mediated by NCOA4." (PMID 40647501, 2025).
poisoning (1 paper, 2024). A condition or physical state produced by the ingestion, injection, inhalation of or exposure to a deleterious agent. "The okadaic acid (OA)-group toxins, including OA, dinophysistoxin-1 (DTX1), dinophysistoxin-2 (DTX2), and dinophysistoxin-3 (DTX3), cause diarrheic shellfish poisoning in humans." (PMID 38147248, 2024).
prostate tumors (1 paper, 2025). "To determine whether the expression of PARP7 and DTX2 affect androgen signaling in human prostate tumors, we focused on the data generated from prostate primary tumors in The Cancer Genome Atlas (TCGA-PRAD)." (PMID 40681873, 2025).
cancer (8 papers, 2019 to 2026). A tumor composed of atypical neoplastic, often pleomorphic cells that invade other tissues. "Although studies addressing the biological differences between the two known DTX2 isoforms are missing, further investigation will eventually clarify each variant’s role and eventual involvement in modulating cancer behavior." (PMID 37443713, 2023). "We initially analyzed the mRNA expression of DTX2 in 33 tumors of various types and corresponding paracancerous tissues obtained from The Cancer Genome Atlas (TCGA) at the pan-cancer level." (PMID 38163902, 2024). "DTX2 has been reported to be involved in many human cancers with functions as an oncogene and can be used as a prognostic marker." (PMID 38163902, 2024). "Human Deltex 2 (DTX2) is a ubiquitin E3 ligase that functions as an oncogene and has been shown to participate in many human cancers." (PMID 38163902, 2024). "Additional studies are needed to clarify the biological weight of DTX2 on telomeres maintenance in a variety of cancer cell types." (PMID 37443713, 2023). "Despite the DTX2 general role in cancer is still unclear, some evidences support a cancer-driving effect." (PMID 37443713, 2023). "GLI3, SMURF1, RBPJL, JAG1, LFNG and DTX2 were some of the most amplified genes present in at least 18 cancers." (PMID 31523055, 2019). "Human DTX2 on chromosome 7 (7q11.23) has been shown to be necessary for cancer cell growth." (PMID 38163902, 2024). "Another general mechanism by which DTX2 may promote cancer progression has been recently suggested by an inducible CRISP/Cas9 screen study disclosing DTX2 promoting role for hTERT transcription and tumorigenesis." (PMID 37443713, 2023). "Finally, DTX2 depletion sensitized cancer cells to X-rays and PARP inhibition and these susceptibilities could be rescued by DTX2 reexpression." (PMID 38992439, 2024). "Therefore, this DTX2 residue embedded in its proline-rich domain could, per se, offer a first hint at DTX2’s potential isoform-specific functional consequences with regard to proliferative disfunctions such as in cancer." (PMID 37443713, 2023). "Collectively, our work uncovers DTX2 as a previously unrecognized regulator of STING, revealing a ubiquitin-dependent mechanism for fine-tuning innate immune response with implications for combating infections and cancer." (PMID 41904156, 2026).
tumor (8 papers, 2020 to 2026). "Univariate and multivariate Cox regression analyses suggested that missing of tumor capsule, a large tumor size, and a high DTX2 expression level could be independent risk factors used to predict survival time in patients." (PMID 39733452, 2025). "Different tumor models in vivo demonstrated that DTX2 inhibitor treatment inhibited tumor growth and sensitized HCC cells to the therapeutic effects of programmed cell death protein 1 (PD‐1) antibody." (PMID 39733452, 2025). "IHC staining of HCC tissue microarray in Zhongshan cohort revealed that a large percentage of the tumor tissues (≈75%) exhibited high DTX2 expression (++/+++)." (PMID 39733452, 2025). "Tumor specimens exhibited elevated expression of DTX2, SALL1, ZNF93, ZNF146 and ZSCAN16, contrasting with reduced levels of EGR2, GATA2, and ZEB2." (PMID 40647501, 2025). "In the orthotopic tumor model, knockdown of Dtx2 or treatment with the mDTX2i increased the efficacy of the PD‐1 antibody." (PMID 39733452, 2025). "In vivo studies using various tumor models demonstrated that treatment with a DTX2 inhibitor not only inhibited tumor growth but also sensitized HCC cells to the therapeutic effects of PD-1 antibodies." (PMID 40387965, 2025). "Correlation analysis showed that IHC score of DTX2 was positively correlated with the number of ARG1+ CD66B+ cells in tumor tissues." (PMID 39733452, 2025). "Tumor size, the expression level of DTX2, and vascular invasion had statistically significant effects on the overall survival of HCC patients." (PMID 39733452, 2025). "The results revealed significant differences in mRNA expression of DTX2 between tumor tissues and their respective paraneoplastic tissues in 16 of the 33 analyzed tumors." (PMID 38163902, 2024). "The qPCR detection of showed that ARG1 and transforming growth factor‐β (TGF‐β) were significantly increased in migrated neutrophils attracted by culture medium of tumor cell overexpressing DTX2, which indicated the pro‐tumoral characteristic of these migrated neutrophils." (PMID 39733452, 2025). "DTX2 is a regulator of the Notch signaling pathway involved in cell fate and tumor immunology." (PMID 34988028, 2021). "Notably, DTX2 exhibited high expression specifically in tumor tissues across all identified cases." (PMID 38163902, 2024). "In addition, Met-1 tumor cells from obese mice expressed significantly higher expression of CSC-associated genes Sox2 and Notch Receptor 2 (Notch2), as well as Notch ligand Dll1 and downstream regulator Dtx2." (PMID 32098183, 2020). "Colony formation and CCK‐8 proliferation assays showed that modulation of DTX2 expression in HCC cells did not significantly affect the growth of tumor cells." (PMID 39733452, 2025). "Multiplex immunofluorescence staining of tumor sections from the Dtx2‐overexpressing group not treated with reparixin revealed that CD8+ T cells, especially IFNγ+ CD8+ T cells, were located mainly at the tumor margins (white arrow point)." (PMID 39733452, 2025). "Moreover, the difference in tumor growth rate between C57BL/6 mice and NOD/SCID mice suggested that DTX2 promoted tumor growth by influencing the immune microenvironment." (PMID 39733452, 2025). "The results suggested that depletion of CD8+ T cells weakened the inhibitory effect of Dtx2 knockdown on tumor growth, while depletion of CD4+ T cells had no such effect." (PMID 39733452, 2025). "CFSE staining showed that the culture supernatant from wild‐type tumor cells and neutrophils inhibited the proliferation of CD8+ T cells, while culture supernatant from DTX2‐knockdown tumor cells and neutrophils partially restored the proliferation of CD8+ T cells." (PMID 39733452, 2025). "Additionally, Deltex E3 ubiquitin ligase 2 (DTX2) in HCC cells has been identified as a promoter of TAN infiltration and polarization toward a pro-tumor phenotype." (PMID 40387965, 2025).
tumor (continued). "Importantly, we discovered TRIM8, DTX2, and TRAF5 as the most vital contributors from the RNF family, which were related to immune infiltration in LGG tumor immune landscape." (PMID 35223862, 2021).
infection (1 paper, 2023). The state of being infected such as from the introduction of a foreign agent such as serum, vaccine, antigenic substance or organism. "Similar to the response to WT STm infection, ΔprgH STm infected 2D enteroids regulated CCL5 and DTX2 at 4 hpi and genes involved in the regulation of antigen presentation (CD83), and inhibition of NFκB activation (NFAIP2)." (PMID 37854334, 2023).
DTX2 also shares sentences with these, for which no sentence is quoted: prostate carcinoma (2 papers); acute myeloid leukemia (1); aortic stenosis (1); astrocytoma (1); basal cell carcinoma (1); breast carcinoma (1); COVID-19 (1); gastric cancer (1); Insulin resistance (1); oligoastrocytoma (1); oligodendroglioma (1); virus infection (1).